PDPN (podoplanin)
Diseases named in the same sentence as PDPN in open-access papers (continued):
Sharing a sentence is not in itself a finding about the gene and the disease.
atherosclerosis (9 papers, 2019 to 2025). A disease characterized by the build-up of fatty material and calcium deposition in the arterial wall resulting in partial or complete occlusion of the arterial lumen. "One of the potential novel markers of atherosclerosis is podoplanin, indicating a possible link between plaque formation and the immune system." (PMID 41465476, 2025). "The PDPN can be regarded as a potential marker of atherosclerosis-related thromboinflammatory crosstalk." (PMID 41465476, 2025). "After plaque rupture in patients with advanced atherosclerosis, PDPN expressed in the plaque binds to CLEC-2 to induce platelet activation, thereby accelerating arterial thrombosis formation." (PMID 38504248, 2024). "The eight major genes upregulated in the carotid vessels (IL18, PDGFRA, IL17, LOX1, TLR4, MYF5, IL1B, and PDPN) were intimately involved in the pathologic progression of atherosclerosis and NIH." (PMID 35531433, 2022). "The accumulation of podoplanin-positive macrophages is observed in many infectious and inflammatory diseases such as peritonitis, lung inflammation, liver infection and atherosclerosis." (PMID 34163489, 2021). "As podoplanin interacts with CLEC-2 present on platelets and can stimulate thrombus formation, it is possible that higher levels podoplanin contributes to thrombosis in advanced stages of atherosclerosis." (PMID 30979062, 2019). "Additionally, podoplanin (PDPN) functioning as an endogenous ligand for C-type lectin-like receptor 2 (CLEC-2) has been identified as a contributor for advanced stage atherosclerosis." (PMID 35531433, 2022). "S100A13 is distributed on the surface of atherosclerosis, and podoplanin is detected in the interior of advanced atherosclerosis, and the different localization of S100A13 and podoplanin may be related to the different effects." (PMID 34177942, 2021). "Podoplanin’s role as a marker of lymphoangiogenesis, inflammation, and platelet activation suggests that reduced PDPN levels in patients with angiographically confirmed atherosclerosis may reflect endothelial dysfunction and impaired vascular remodeling, including lymphoangiogenesis." (PMID 41465476, 2025). "Our results in this study indicate that interaction of platelet CLEC-2 with PDPN on monocytes/macrophages plays a major role in the formation of monocyte/macrophage-platelet aggregates and their subendothelial accumulation in the development of atherosclerosis in mice." (PMID 34815786, 2021). "In conclusion, we show a novel, key immunomodulatory role for CLEC-2-podoplanin interaction to limit the accumulation and retention of highly inflamed macrophages in tissues, a major complication observed in many sterile thromboinflammatory diseases such as atherosclerosis and metabolic syndrome." (PMID 34163489, 2021). "It was previously proposed that the interaction between PDPN on activated macrophages and platelet CLEC-2 played a role in thromboinflammation under atherosclerosis conditions and, thus, contributed to the thrombotic properties of advanced atherosclerotic lesions." (PMID 37047799, 2023). "Furthermore, only podoplanin-positive macrophages were able to bind and activate platelets via CLEC-2, suggesting a role of the podoplanin–CLEC-2 axis for extravascular platelet activation during clotting, i.e., wound healing and inflammatory processes such as atherosclerosis." (PMID 30736372, 2019).
germ cell tumor (9 papers, 2007 to 2024). A benign or malignant, gonadal or extragonadal neoplasm that originates from germ cells. "D2-40/podoplanin is a monoclonal antibody of subclass IgG2a; it is directed against the M2A oncofetal antigen that is usually expressed in germ cell tumors and fetal testis tissue." (PMID 24040306, 2013). "Afterwards, it was also demonstrated that D2-40 and anti-podoplanin had similar expression of its antigens (M2A and podoplanin, respectively) in human developing testis, testicular carcinoma in situ and germ-cell tumors." (PMID 18072963, 2007).
venous thromboembolism (9 papers, 2018 to 2025). Occlusion of the lumen of a vein by a thrombus that has migrated from a distal site via the blood stream. "Studies have indicated that the high expression of PDPN in tumors is associated with an increased risk of venous thromboembolism (VTE) in GBM patients." (PMID 39682237, 2024). "For example, the up-regulation of PDPN by cancer cells has recently been linked to an increased risk for venous thromboembolism in GBM." (PMID 36199581, 2022). "Altogether, these studies point to podoplanin as a potential biomarker to predict and identify patients at increased risk of cancer-associated venous thromboembolism." (PMID 30736372, 2019). "Secondly, podoplanin can be released from tumor cells attached to the membrane of extracellular vesicles, and circulating microparticles are associated with venous thromboembolism in cancer patients." (PMID 30736372, 2019). "Podoplanin is widely expressed in the brain, lung, heart, kidney, bone, and lymphoid organs, and high expression of podoplanin is associated with an increased risk of venous thromboembolism in tumor patients." (PMID 35936717, 2022). "Furthermore, PDPN induces platelet aggregation through interaction with CLEC-2 on platelets, which is associated with venous thromboembolism and evasion of immune cells." (PMID 37894446, 2023). "Podoplanin (PDPN), a ligand of the C-type lectin receptor (CLEC-2), promotes platelet activation, aggregation, venous thromboembolism (VTE), lymphatic vessel formation, and tumor metastasis in GBM patients." (PMID 39682237, 2024).
Arthritis (8 papers, 2016 to 2026). Inflammation of a joint. "Injecting PDPN+FAPα+THY1− or PDPN+FAPα+THY1+ cells into the inflamed ankle joint of mice is a different method for investigating arthritis degeneration processes." (PMID 36232468, 2022). "Stromal cell markers CD55, CD248, FAP and podoplanin are expressed in the earliest stage of arthritis." (PMID 30847027, 2019). "Stromal cell markers CD55, CD248, FAP and podoplanin are expressed in ST in the earliest stage of arthritis." (PMID 28793332, 2017). "Additionally, the Maackia amurensis seed lectin (MASL), that can be utilized to target PDPN, attenuates the inflammatory response mediated by NF-kB activation in primary chondrocytes and protects human cartilage breakdown ex vivo and in an animal model of arthritis." (PMID 32326143, 2020). "Synovial tissue expression of stromal markers in early arthritis was analyzed using immunofluorescence to detect stromal markers CD55, CD248, fibroblast activation protein and podoplanin." (PMID 30847027, 2019). "Of them, circulating fibroblasts (podoplanin+CD45-CD3-CD19-CD4-CD8-CD56-CD66b-CD294-) co-expressing CDH11 and C-C Chemokine Receptor 7 (CCR7) were found exclusively in arthritis patients' blood." (PMID 41624850, 2026). "Since we found upregulation of podoplanin in ST of patients with early RA, the involvement of this marker in an EMT-like differentiation of RA-FLS into myofibroblasts could be of importance in the earlier stages of arthritis." (PMID 28793332, 2017). "ST from 56 patients included in two different early arthritis cohorts and 7 non-inflammatory controls was analysed using immunofluorescence to detect stromal markers CD55, CD248, fibroblast activation protein (FAP) and podoplanin." (PMID 28793332, 2017).
bladder cancer (8 papers, 2014 to 2022). "Because pulmonary metastasis of PDPN-positive bladder cancer cells was reduced by the knockdown of PDPN and the administration of anti-PDPN neutralizing antibodies in mice models, targeting platelet–cancer cell interactions would be promising for an antimetastatic approach." (PMID 34302117, 2021). "Newly discovered CLEC-2 and its activator, podoplanin (PDPN) – expressed on multiple tumor cells (e.g. colorectal, lung and bladder carcinomas), are key in platelet aggregation and seem to be important in platelet-cancer cell interaction." (PMID 33146401, 2021).
brain cancer (8 papers, 2016 to 2025). A primary or metastatic malignant neoplasm affecting the brain. "Additionally, increased expression of brain tumor podoplanin has been found to be associated with increased risk of VTE in patients with primary brain cancer." (PMID 32707653, 2020). "Interestingly, we could show in a previous study that low platelet counts are linked to podoplanin expression and to high VTE risk in brain cancer patients, suggesting that high platelet activation due to podoplanin leads to platelet consumption." (PMID 38613361, 2024).
invasive ductal carcinoma (8 papers, 2013 to 2025). "A previous study investigating CAFs from invasive ductal carcinoma of the pancreas investigated the impact of different culture conditions on levels of PDPN expression." (PMID 40640541, 2025). "A previous study pointed out that PDPN‐expressing CAFs facilitated the development of invasive ductal carcinoma." (PMID 36156321, 2023). "Using IHC, we also analyzed the presence of podoplanin expressing CAFs in peripheral stroma at the margin of tumor and tumor stroma in the same paraffin sections of invasive ductal carcinoma (IDC)." (PMID 28938000, 2017). "In this study, we examined PDPN expression in invasive ductal carcinoma (IDC) of the human pancreas using immunohistochemical methods, and investigated the functional roles of PDPN-expressing CAFs established from pancreatic IDCs by cell sorting." (PMID 24354864, 2013). "An interesting observation in this report is that the numbers of podoplanin-positive CAFs were significantly higher in invasive ductal carcinomas with respect to non-invasive ductal carcinomas in situ, and these podoplanin-positive CAFs co-localized with blood vessels only in the former tumors." (PMID 30736372, 2019).
malignant pleural mesothelioma (8 papers, 2014 to 2025). A malignant neoplasm that arises from mesothelial cells in the pleura and shows a diffuse growth pattern. "The cytotoxic effects of NIR-PIT targeting PDPN with NZ-1 have been reported in malignant pleural mesothelioma." (PMID 41011286, 2025). "The cytotoxic effects of NIR-PIT targeting PDPN with NZ-1 antibody have been reported in malignant pleural mesothelioma." (PMID 41011286, 2025). "Among them, an anti-PDPN antibody (clone NZ-1.2) effectively captured PDPN-high CTCs in peripheral blood from 15 of 22 malignant pleural mesothelioma (MPM) patients." (PMID 35159384, 2022). "In our previous study, a microfluidic system was developed based on podoplanin detection for capturing circulating tumor cells (CTCs), derived from malignant pleural mesothelioma (MPM)." (PMID 34025789, 2021).
autoimmune disease (7 papers, 2015 to 2025). A disorder resulting from loss of function or tissue destruction of an organ or multiple organs, arising from humoral or cellular immune responses of the individual to their own tissue constituents. "PDPN’s involvement in lymphoangiogenic processes in autoimmune diseases is associated with clinical severity and lymphatic vessel density." (PMID 41465476, 2025). "High expression of podoplanin has been associated with different autoimmune diseases, inflammation, and cancer cell invasion and metastasis." (PMID 32533757, 2020). "The expression of podoplanin was found to be upregulated in Th17 cells and other cell types associated with different autoimmune diseases." (PMID 30736372, 2019). "Comparing the virus-induced LucAdV5 mouse model with the spontaneous NZBW-F1 mouse model of human SLE and Sjögren’s disease, we describe the involvement of macrophages in pathogenesis of these two autoimmune diseases with focus on their expression of PDPN." (PMID 39355243, 2024). "The podoplanin+ Th17 cells induce the formation of ectopic lymphoid-like structures (ELS) at inflamed sites of autoimmune diseases, such as RA, multiple sclerosis, systemic lupus erythematosus, and myasthenia gravis." (PMID 30800133, 2019). "Increased podoplanin immunostaining was found in the salivary glands of patients with primary Sjögren syndrome, an autoimmune disease of the exocrine glands of unknown ethyology." (PMID 30736372, 2019). "In addition, PDPN is a known regulator of TH17 cells, which play an important role in the pathophysiology of autoimmune diseases such as MS." (PMID 35592112, 2022).
malignant glioma (7 papers, 2015 to 2025). A grade III or grade IV glioma arising from the central nervous system. "Podoplanin (PDPN) is a membrane glycoprotein implicated in tumor invasion and immune modulation in high-grade gliomas (HGGs)." (PMID 40554484, 2025). "Elevated PDPN expression has been reported to correlate with short-term survival among malignant glioma patients." (PMID 36059614, 2022). "Of the 12 overexpressed genes, ABCC3, COL8A1, IBSP and PDPN are reportedly associated with GBM, while CTHRC1, PDLIM4 and MYL9 are associated with high-grade and malignant gliomas, respectively." (PMID 35456975, 2022). "To validate the prognostic significance of PDPN across malignant gliomas, we examined a cohort of 93 WHO grade II/III diffuse astrocytomas." (PMID 36059614, 2022). "The anti-PDPN antibodies NZ-1 that are either radiolabeled with N-succinimidyl 4-guanidinomethyl 3-[131I]iodobenzoate or fused to Pseudomonas exotoxin A carrying a C-terminal KDEL peptide exhibited significant suppression in the tumor growth of malignant glioma." (PMID 26528756, 2015).
respiratory failure (7 papers, 2006 to 2023). The significant impairment of gas exchange within the lungs resulting in hypoxia, hypercarbia, or both, to the extent that organ tissue perfusion is severely compromised. "Podoplanin-deficient mice die at birth owing to respiratory failure exhibiting a phenotype of dilated, malfunctioning lymphatic vessels and lymphoedema." (PMID 20196862, 2010). "Podoplanin KO mice die after birth due to respiratory failure, with defective differentiation of type I alveolar cells." (PMID 37386100, 2023). "However, the function of podoplanin in other podoplanin-positive organs, particularly in the hard tissue, has not been established as podoplanin absence is lethal to mice because of the occurrence of respiratory failure at birth as mice lines with podoplanin-floxed alleles have not yet." (PMID 28222099, 2017). "Physiologically podoplanin functions during development, as podoplanin null mice show increased embryonic lethality with disorder in heart development or die after birth owing to respiratory failure and not inflated lung." (PMID 28674748, 2017). "However, little is known about the functions of podoplanin in the somatic cells of the adult organism because an absence of podoplanin is lethal at birth by the respiratory failure." (PMID 28222099, 2017).
skin tumors (7 papers, 2007 to 2024). "However, the increased risk of carcinogenesis due to podoplanin upregulation should be considered, because a chronic wound in itself is a risk factor for skin cancers." (PMID 35163233, 2022). "They observed that PDPN expression in skin tumors was dependent on Fos, especially when induced by 12-O-tetradecanoylphorbol-13-acetate." (PMID 40741180, 2024). "In skin cancers, podoplanin expresses on tumor cells and promotes their migration and epithelial-mesenchymal transition, thereby accelerating invasion and metastasis." (PMID 35163233, 2022). "In the mouse model, FOS-dependent PDPN expression was observed in mouse skin tumors induced by 12-O-tetradecanoylphorbol-13-acetate (TPA)." (PMID 35159384, 2022). "Taken together, these data suggest that keratinocyte-expressed podoplanin is dispensable for skin tumor initiation, growth and malignant transformation in the two-stage chemical carcinogenesis model." (PMID 32599908, 2020). "Studies indicate that PDPN expression is strongly induced in about 80% of skin cancers." (PMID 22844530, 2012). "Of 28 skin cancer samples analysed, 79% expressed podoplanin." (PMID 17179989, 2007).
vascular tumors (7 papers, 2008 to 2026). "From a physiological standpoint, D2-40 (podoplanin) plays a significant role in increasing endothelial cell adhesion and serves as a marker for lymphatics and lymphatic differentiation within vascular tumors." (PMID 37894944, 2023). "D2-40 (podoplanin) has been reported to highlight not only a variety of vascular tumors but is a useful tool in distinguishing PAC and other cutaneous tumors from metastatic adenocarcinoma to the skin." (PMID 34771579, 2021).
Autoimmunity (6 papers, 2012 to 2025). The occurrence of an immune reaction against the organism's own cells or tissues. "In T cell-specific PDPN-deficient mice, loss of PDPN exacerbates autoimmunity, while overexpression inhibits T cell responses and mitigates neuroinflammation." (PMID 41573582, 2025). "In autoimmunity, the reticular network organization was altered, displayed lower expression of PTAs and podoplanin, and, in this context, IL-17 signaling impacted LN stromal organization, leading to highly metabolically activated FRCs." (PMID 34068712, 2021). "Furthermore, our finding that CLEC-2 protein by itself and podoplanin antibody are capable of inducing T regs identifies novel approaches for induction of Tregs for immunotherapy against transplantation and autoimmunity." (PMID 26416420, 2015). "Some forms of Inflammation recapitulate the formation of lymphoid stromal cells as the accumulation of podoplanin positive stromal cells was demonstrated in different inflammatory models in the mouse (e.g. models of autoimmunity, inflammation of mouse ears induced by adjuvant)." (PMID 23300922, 2012). "While the in vivo functions of PDPN expression by hematopoietic cells have not been fully elucidated, interesting implications abound given what is known about PDPN function in cancer and autoimmunity." (PMID 22988448, 2012).